SDC4 (syndecan 4)
Diseases named in the same sentence as SDC4 in open-access papers (continued):
Sharing a sentence is not in itself a finding about the gene and the disease.
ischemic disease (1 paper, 2015). Lack of blood supply to an area of the body, resulting in impairment of tissue oxygenation. "Altogether, these data indicate that EXT2, HPSE, and SDC-4 are involved in the proangiogenic effects of LMWF, suggesting that the HS metabolism changes linked to LMWF-induced angiogenesis offer the opportunity for new therapeutic strategies of ischemic diseases." (PMID 26516869, 2015).
Jaundice (1 paper, 2023). Yellow pigmentation of the skin due to bilirubin, which in turn is the result of increased bilirubin concentration in the bloodstream. "PCR results showed that SDC4 expression of liver tissues was significantly higher in jaundice group compared with jaundice-free group." (PMID 36816373, 2023).
keloid (1 paper, 2022). An irregularly shaped, elevated mark on the skin caused by deposits of excessive amounts of collagen during wound healing. "In this present study, innovatively combining SVM-RFE and LASSO-logistic regression methods, we identified four biomarkers (STC2, SDC4, DAAM1, and NOX4) for keloid and further explored the role of ICI on keloid." (PMID 35719372, 2022). "Compared to normal group, the relative expression levels of SDC4, NOX4, DAMM1, and STC2 in keloid fibroblasts were 0.28 ± 0.13, 2.07 ± 0.32, 2.11 ± 0.63, and 1.87 ± 1.56, respectively." (PMID 35719372, 2022). "In addition, we also conducting a qRT-PCR experiment for detecting differential expression of SDC4, NOX4, DAMM1, and STC2 between keloid and normal tissue." (PMID 35719372, 2022).
kidney failure (1 paper, 2016). An acute or chronic condition that is characterized by the inability of the kidneys to adequately filter the blood. "The other reason may be the accumulation of syndecan-4 as a result of kidney failure, however, according to our knowledge, the effect of renal function and influence of HD process on syndecan-4 metabolism remains unknown." (PMID 27685148, 2016).
Lewis lung carcinoma (1 paper, 2021). "The importance of syndecan-4 for the communication between tumor cells and immune cells has also been highlighted in vivo, as syndecan-4-deficient mice show reduced Lewis lung carcinoma growth, less dendritic cell recruitment, and increased recruitment of natural killer cells." (PMID 33810567, 2021).
listeriosis (1 paper, 2020). A bacterial infection caused by Listeria monocytogenes. "This phenotype is not seen in Sdc3-/- or Sdc4-/- mice, indicating that ablation of Sdc1 causes a specific gain of function that enables mice to resist listeriosis." (PMID 32453780, 2020).
liver diseases (1 paper, 2011). "Biomarkers previously associated with liver diseases and identified in our samples were among others: ANGPTL3, IGFBP2, SDC4, IL1RN." (PMID 21978410, 2011).
lymph node disease (1 paper, 2013). "Our data suggest that syndecan-4 represents a biological marker in patients with TGCTs and further studies can be performed in order to determine the clinical utility of syndecan-4 expression in predicting occult lymph node disease in patients with stage I NSGCTs." (PMID 23844358, 2013).
lymph node metastasis (1 paper, 2022). "Moreover, COX regression analysis showed that lymph node metastasis and SDC4 expression were independent risk factors affecting the prognosis of PAAD patients." (PMID 36199068, 2022).
muscle disorders (1 paper, 2020). "Consistent with the previous report, we did not observe any centrally nucleated myofibers in the syndecan-4–/–, a characteristic often associated with muscle disorders and impaired maintenance of MuSC quiescence." (PMID 32850844, 2020).
myeloid leukemia (1 paper, 2020). A clonal proliferation of myeloid cells and their precursors in the bone marrow, peripheral blood, and spleen. "We should note that other syndecan family members may also contribute to myeloid leukemia, since knockdown of SDC2, SDC3, SDC4 either individually or in combination led to significant growth inhibition." (PMID 33243988, 2020).
osteomyelitis (1 paper, 2026). An acute or chronic inflammation of the bone and its structures due to infection with pyogenic bacteria. "We identified that significant infiltration of Arg1+Sdc4+, Cxcl1+Ccl4+, and Mif+Cd63+ macrophages may affect osteomyelitis through the Ccl3-Ccr1 and Cxcl2-Cxcr2 signaling pathways." (PMID 41836400, 2026).
peritonitis (1 paper, 2026). Inflammation of the peritoneum (tissue that lines the abdominal wall and covers most of the organs in the abdomen). "Furthermore, the SDC4 EVs showed anti-inflammatory effects in vivo in a model of peritonitis." (PMID 41926337, 2026).
pulmonary hypertension (1 paper, 2022). Increased pressure within the pulmonary circulation due to lung or heart disorder. "SDC4 has not been studied in pulmonary hypertension and may promote vascular remodeling by mediating collagen synthesis." (PMID 36171892, 2022).
renal fibrosis (1 paper, 2020). A final common manifestation of a wide variety of chronic kidney diseases characterized by glomerulosclerosis and tubulointerstitial fibrosis. "IFN-γ can induce the production of profibrotic factors, such as transglutaminase 2 (TG2) and the heparan sulfate proteoglycan syndecan-4 (sdc4) that contribute to the accumulation of extracellular matrix, thus favoring the development of renal fibrosis." (PMID 32903887, 2020).
scrapie (1 paper, 2010). A fatal disease of the nervous system in sheep and goats, characterized by pruritus, debility, and locomotor incoordination. "Comparing the prp2 morphant with the mouse scrapie model revealed 5 genes in common: GFAP, CD9 antigen (CD9), solute carrier family 14 member 1 (SLC14A1), heat shock 22kDa protein 8 (HSPB8) and syndecan 4 (SDC4)." (PMID 21042590, 2010).
skin cancer (1 paper, 2023). "Similarly, THBS1, SDC4, and TLN1 have been linked to the development of metastasis and chemoresistance in skin cancer." (PMID 37510272, 2023).
Stroke (1 paper, 2023). Sudden impairment of blood flow to a part of the brain due to occlusion or rupture of an artery to the brain. "AZ_628, which screened from CMap analysis, was found to have lower binding energy with Mmp12, Lgals3, Fam20c, Capg, Pkm2, Sdc4, and Itga5 in microglia subcluster 2 and maybe a therapeutic agent for the poor development of microglia subcluster 2 after stroke." (PMID 38067435, 2023).
testicular germ cell tumours (1 paper, 2013). "Although syndecan-4 is implicated in cancer progression, there is no information for its role in testicular germ cell tumours (TGCTs)." (PMID 23844358, 2013).
triple-negative breast carcinoma (1 paper, 2023). An invasive breast carcinoma which is negative for expression of estrogen receptor (ER), progesterone receptor (PR), and human epidermal growth factor receptor 2 (HER2). "Different studies show that a higher expression of SDC4 in the subgroup of ER/PR-negative and triple-negative breast cancer patients is correlated with poor survival rates." (PMID 36980680, 2023). "A recent study showed that the cell cycle of triple-negative breast cancer cells is regulated by a complex formed by the docking of EGFR with the extracellular domain of SDC4 (engaged with α3β1 and α6β4 integrins), followed by the incorporation of SDC2, RON tyrosine kinase, and ABL1." (PMID 36980680, 2023).
tuberculosis (1 paper, 2024). A chronic, recurrent infection caused by the bacterium Mycobacterium tuberculosis. "The THBS signaling pathway is widely present in the region enriched with macrophages in the tuberculosis spot, indicating that macrophages and fibroblasts interact depending on THBS1/2-CD36/SDC4/ITGA3/ITGB1, which may be a key pathway for tuberculosis progression." (PMID 39431015, 2024).
tumor (96 papers, 2008 to 2026). "ANGPTL4, expressed by ECs, has been associated with tumor angiogenesis and metastasis, whereas SDC4, expressed by cancer cells, is upregulated in GC and linked to invasion." (PMID 41154806, 2025). "Ki Yong Na and colleagues showed that strong SDC4 expression was associated with the occurrence of distant metastasis and large tumor size in OS, indicating that the increased expression of SDC4 accounts for more aggressive clinical behavior in OS." (PMID 37935976, 2024). "In this review, we demonstrated that changes in the expression of syndecan-4 contribute to the development and progression of cancer, and have a diagnostic and prognostic value in numerous tumor entities." (PMID 33810567, 2021). "Changes in SDC4 expression contribute to cancer growth and progression and have diagnostic and prognostic significance in numerous tumor types." (PMID 34282767, 2021). "In the following section, we will highlight the role of syndecan-4 in selected tumor-associated cellular functions." (PMID 33810567, 2021). "A clear trend for correlation of lower tumour cells associated staining for syndecan-4 with tumour size and distant metastases was observed as well, but no statistical significance was reached." (PMID 23844358, 2013). "Taken into account the proved role of syndecans in malignancies and the structure/function similarities among syndecans we aimed to study the expression profile of syndecan-4 in TGCTs as well as its association with the metastatic potential of these tumours." (PMID 23844358, 2013). "The aim of the present study was to investigate the expression of syndecan-4 in seminomatous and NSGCTs and to examine all possible associations with the malignant behavior of these tumours." (PMID 23844358, 2013). "This loss of syndecan-4 by tumour cells in NSGCTs was associated with nodal metastasis (P = 0.01), vascular and lymphatic invasion (P = 0.01), and disease stage (P = 0.01)." (PMID 23844358, 2013). "In NSGCTs less tumour cell associated staining for syndecan-4 was observed in patients with advanced disease stage." (PMID 23844358, 2013). "SDC4 modulates several steps in the development and progression of tumors, such as uncontrolled cell proliferation, invasive growth, migration, metastases formation, angiogenesis, as well as tumor-associated inflammation." (PMID 34282767, 2021). "The unique association of SDC4 may reflect its distinct role in cellular processes, including extracellular matrix remodeling and growth factor signaling, potentially linked to HR + tumor biology." (PMID 40694191, 2025). "Tumours with SDC4::NRG1 fusions also overexpress HER2 pathway-related genes, reinforcing NRG1-driven activation." (PMID 41914575, 2026). "Previously, we demonstrated that the SDC4 gene is amplified in 28% of human FNRMS samples, associated with high mRNA expression, suggesting a tumor driver role." (PMID 40076757, 2025). "In melanoma, tumor-derived GPNMB engages Syndecan-4 on T cells to blunt antitumor immunity, with knockout studies demonstrating >50% reduction in B16F10 tumor growth." (PMID 41180454, 2025). "MDK expressed by tumor cells can promote enhanced Treg infiltration by promoting Treg motility, with syndecan 4 (SDC4) serving as the putative receptor for MDK on Treg cells." (PMID 40429950, 2025). "In the hypoxic Pseudo.A region, ITGA5 and SDC4 showed enhanced abundance in subtype 2 TCs in comparison to CLEC5A which was enriched in tumor infiltrating MG/MØs, and LGALS3 that was overall higher in both TCs and surrounding stromal cell types." (PMID 41366031, 2025). "The silencing of syndecan-4 impeded these processes and diminished the invasive potential of tumour cells, underscoring its role in shaping the formation of alternative vascular networks supporting tumour growth." (PMID 41463344, 2025).
tumor (continued). "By affecting several signaling pathways and biological processes such as cell proliferation, migration, metastasis formation, and angiogenesis, SDC4 is also highly involved in tumor progression and development." (PMID 40076757, 2025). "Our data revealed that secretion of multiple ligands by macrophages, endothelial cells, and fibroblasts converge on the same receptors, such as SDC1 and SDC4 on tumor cells." (PMID 38546390, 2024). "Exosomal miR-194-5p derived from dying pancreatic cancer induced DNA damage response in tumor-repopulating cells to promote tumor repopulation, and its exosome target SDC4 was identified." (PMID 37569824, 2023). "It has been reported that the overexpression of SDC4 in tumorigenesis is stimulated by tumor-suppressor molecules." (PMID 38067582, 2023). "Our study suggests that syndecan-4 can serve as a tumor driver gene in promoting rabdomyosarcoma tumor development." (PMID 35128576, 2022). "The present study found that the knockdown of syndecan-4 expression attenuated TN-C-induced tumor migration, invasion and proliferation, suggesting that TN-C contributes to metastasis and proliferation in a manner that is dependent on syndecan-4." (PMID 35246056, 2022). "Subsequently, we categorized the PAAD patients into the high SDC4 expression and low SDC4 expression groups and found that SDC4 expression had correlations with tumor differentiation, tumor TNM stage, and lymph node metastasis." (PMID 36199068, 2022). "The differential analysis of TCGA-PAAD cohort showed that SDC4 expression in tumor patients was increased compared with the control group (P < 0.01)." (PMID 36199068, 2022). "SDC4 mediates the uptake and internalization of hydroxyapatite nanoparticles or exosomes in tumor cells, which are promoted by methemoglobin-A (fetuin-A) and histones." (PMID 36358833, 2022). "We detected syndecan-4 copy-number amplification in 28% of FNRMS cases accompanied by high levels of syndecan-4 expression suggesting that syndecan-4 can serve as a tumor driver gene in promoting rabdomyosarcoma development." (PMID 35128576, 2022). "Further in vitro mechanistic analyses revealed that TN-C, as an ECM component, activated NF-κB signaling by binding with syndecan-4 to promote tumor progression." (PMID 35246056, 2022). "An ECM component, Tenascin-C, which has been reported to compete with the binding sites of fibronectin with SDC4, is recently reported to activate NF-κB signaling by binding with SDC4 to promote tumor progression." (PMID 36358833, 2022). "It has already been demonstrated that the SDC4 exhibited multiple functions in tumor pathogenesis and progression, but the in-depth knowledge about SDC4 is still very limited." (PMID 35757722, 2022). "SDC4 mediates the uptake and internalization of hydroxyapatite nanoparticles or exosomes in tumor cells, promoted by fetuin-A and histone." (PMID 36358833, 2022). "In non-tumor tissues, Sdc1, Sdc2, Sdc3, Sdc4, and Sdcbp were expressed in all four prostate lobes, with no significant quantitative difference among them." (PMID 34445387, 2021). "SDC4 expression is dysregulated in several tumor types, in most cases the tumor cells exhibit SDC4 overexpression." (PMID 34282767, 2021). "In both seminomatous testicular germ cell tumors (TGCTs) and nonseminomatous germ cell tumors (NSGCTs), significantly increased expression of syndecan-4 was detected in tumor cells." (PMID 33810567, 2021). "Calumenin inhibits cell migration and tumor metastasis through FN, SDC4 and α5β1-integrin by the suppression of ERK1/2 signaling." (PMID 34282767, 2021). "Increased expression of SDC4 is observed in endothelial cells after tumor cell seeding to the lungs." (PMID 34282767, 2021). "In this review, we discuss the SDC4-mediated cell migration focusing on the role of SDC4 in tumor cell movement." (PMID 34282767, 2021).
tumor (continued). "The authors attributed the loss of SDC4 staining on the surface of tumor cells to the aggressiveness and stage of tumor progression, with higher expression of SDC4 in less-aggressive tumors." (PMID 34445387, 2021). "The multiple roles of SDC4 in tumor pathogenesis and progression has already been demonstrated; therefore, the expression and signaling of SDC4 was investigated in several tumor types." (PMID 34282767, 2021). "The dysregulated expression of syndecan-4 in numerous tumor entities suggests a possible mechanistic contribution to cancer progression." (PMID 33810567, 2021). "The SDC4-α5β1 integrin signaling through PKCα participates in TG2/S100A4-mediated tumor cell migration." (PMID 34282767, 2021). "The dysregulation of syndecan-4 in various cancers, and its mechanistic contribution to multiple steps of tumor progression, mark it as an attractive potential target for cancer therapy." (PMID 33810567, 2021). "The high expression of SDC1 and SDC4 indicates proliferation, metastasis and drug resistance of tumor cells, which will result in a poor prognosis." (PMID 35127731, 2021). "SDC4 influences tumor progression by regulating cell proliferation as well as cell migration by affecting cell-matrix adhesion and several signaling pathways." (PMID 34282767, 2021). "Increased levels of SDC4 expression were found in response to lung injury, as well as after tumor cell seeding." (PMID 34282767, 2021). "Beyond the role of SDC4 in tumor cell migration, SDC4 was shown previously to affect migration in various non-cancerous cell types as well, including fibroblasts, myoblasts, endothelial cells, or hepatic stellate cells." (PMID 34282767, 2021). "The pattern of expression of Sdc-4 in tumor infiltrating cells is similar to that of Sdc-3, with the exception of a higher expression on CAFs." (PMID 33117401, 2020). "Here we also show that Sdc-4 correlates with a hypoxia signature and gets upregulated on tumor cells upon inhibition of PHDs." (PMID 33117401, 2020). "There is evidence showing that EV-associated histones have a pro-inflammatory activity and can mediate the endocytosis/uptake of EVs by tumor cells that express syndecan-4." (PMID 31454892, 2019). "Overall, syndecan-4 is a versatile molecule regarding tumor progression and more studies on its roles in cell physiology and the changes that accompany an invasive phenotype are needed for further advances in this field." (PMID 26558271, 2015). "SDC4 has been proposed to be a sensor of tension exerted on the extracellular matrix, which is an important event in wound contraction, tumor-stroma interactions, fibrosis and the regulation of motility." (PMID 26317806, 2015). "Syndecan-4 physiological role in focal adhesion formation can also be translated into tumor progression." (PMID 26558271, 2015). "Several studies have correlated the overexpression of syndecan-4 with increased tumor cell proliferation." (PMID 25549223, 2014). "Changes in the expression of syndecan-4 have been observed in tumor cells, indicating its involvement in cancer." (PMID 25549223, 2014). "Although various studies have focused on the role of other syndecans in malignancies, little is known about the role of syndecan-4 in tumour development." (PMID 23844358, 2013). "Syndecan-4 interacts with chemokines through HS chains and promotes tumour cell migration and invasion but also regulates the invasion of K-ras mutant cells in collagen lattice together with integrin α2β1 and MT1-MMP." (PMID 23844358, 2013). "The expression of syndecan-4 in the tumour stroma was correlated with the microvessel density in TGCTs." (PMID 23844358, 2013). "Our study revealed that seminomatous TGCTs are characterized by much higher staining of syndecan-4 in tumour cells compared to NSGCTs." (PMID 23844358, 2013). "To evaluate the expression of syndecan-4 by tumour and stromal cells, we performed immunohistochemistry in tissue sections." (PMID 23844358, 2013).